TLR7 (toll like receptor 7)
Diseases named in the same sentence as TLR7 in open-access papers (continued):
Sharing a sentence is not in itself a finding about the gene and the disease.
COVID-19 (continued). "There was positive significant correlation between Neutrophil–lymphocyte ratio and mRNA expression of TLR3 (rho = 0.62, P = 0.012), TLR7 (rho = 0.60, P = 0.013), TLR8 (rho = 0.49, P = 0.011), and TLR9 (rho = 0.39, P = 0.036) in all COVID-19 cases." (PMID 35538443, 2022). "TLR7 has also been shown to activate in response to SARS-CoV-2, and abnormalities in the TLR7 gene correlate with severe COVID-19." (PMID 35955740, 2022). "It was seen that the transcript levels of TLR3, TLR7, TLR8, and TLR9 were overexpressed in the COVID-19 patients with clinical symptoms needing hospitalization as well as in those with clinical symptoms without needing for hospitalization compared to controls." (PMID 35538443, 2022). "Significant upregulation of STING, IRF3, TLR7, MAVS, and IFNβ expression was found in COVID-19 exposed placentas vs. controls (p<0.01 for STING, TLR7, MAVS, and IFNβ, and p<0.05 for IRF3)." (PMID 36743911, 2022). "In family n°12, also the p.Gln11Leu in TLR7 and p.Ala114Ser in IL1A co-segregated with COVID-19 positive status." (PMID 36228008, 2022). "We observed that TLR7, together with MAVS, TLR9, IRF7, was downregulated in pDCs in the COVID-19 groups but more so in the groups with severe disease." (PMID 36439166, 2022). "The mRNA expression of TLR3 (fold change = 3.4, P = 0.032), TLR7 (fold change = 2.0, P = 0.041), TLR8 (fold change = 2.8, P = 0.019), and TLR9 (fold change = 2.1, P = 0.016) was significantly upregulated in COVID-19- Group A compared with the Control-Group I." (PMID 35538443, 2022). "More specifically, TLR3, TLR7, TLR8, and TLR9 were upregulated in the COVID-19 cases with clinical symptoms and needing hospitalization as well as in those with clinical symptoms but without requirement for hospitalization for supportive cares." (PMID 35538443, 2022). "There was positive significant correlation between ESR and mRNA expression of TLR3 (rho = 0.71, P = 0.005), TLR7 (rho = 0.62, P = 0.011), TLR8 (rho = 0.65, P = 0.029), and TLR9 (rho = 0.40, P = 0.044) in all COVID-19 cases." (PMID 35538443, 2022). "Data for the M1 mask for TLR7 and MARK1 in the severe COVID-19 phenotype was then replicated with the GenOMICC cohort, a prospective study enrolling critically ill individuals with COVID-19, with controls selected from the 100,000 genomes cohort." (PMID 36327219, 2022). "Gene analysis also revealed elevated expression of TLR7 and TLR9, leading to exaggerated immune response, in certain ethnic groups with higher COVID-19 mortality." (PMID 35956081, 2022). "A significant positive correlation was observed between CRP and mRNA expression of TLR3 (rho = 0.85, P = 0.001), TLR7 (rho = 0.80, P = 0.004), TLR8 (rho = 0.78, P = 0.010), and TLR9 (rho = 0.48, P = 0.035) in the all COVID-19 cases." (PMID 35538443, 2022). "In conclusion, our investigation indicated that the mRNA expressions of TLR3, TLR7, TLR8, and TLR9 are upregulated in the nasopharyngeal epithelial cells from COVID-19 patients." (PMID 35538443, 2022). "We found that, even in absence of a productive viral replication, the virus mediates a vigorous TLR7/8-dependent production of both type I and III IFNs and inflammatory cytokines and chemokines, known to contribute to the cytokine storm observed in COVID-19." (PMID 34473805, 2021). "Currently, a phase II clinical trial of a TLR7 antagonist (NCT04448756) is being completed, which investigated the antagonist’s possibilities in modulating the CS and immunopathology in severe COVID-19 patients." (PMID 34858409, 2021). "TLR7 codes for a Toll-like receptor that can recognise single-strand RNA present in viruses such as SARS-CoV-2, the agent responsible for COVID-19." (PMID 33752797, 2021). "We observed markedly elevated cytokine responses in COVID-19 patients upon Toll-like receptor 4 (TLR4) activation by lipopolysaccharide (LPS) and TLR7/8 activation by R848." (PMID 33377122, 2020).
COVID-19 (continued). "We concluded that TLR-7 and TLR-4 agonists may be effective adjuvants in COVID-19 vaccines for mounting immunity that is long-lasting against SARS-CoV-2 infection." (PMID 38543837, 2024). "Clearly, the presence of non-functional mutant TLR7/8 variants or reductions in their expression leads to deficient IFN-λ or IFN-I production and is associated with severe COVID-19." (PMID 39062904, 2024). "As would be expected from the SARS-CoV-2 viral activation pattern just described, TLR3, TLR7, TLR8, TLR9, NLRP3, RIG-1 and MDA-5 are activated in patients with severe COVID-19." (PMID 36769320, 2023). "Recent studies demonstrated that mutations of TLR3 and TLR7 and some of the downstream signaling molecules required for type I IFNs production are correlated with the severity of COVID-19, indicating the critical roles of TLR3 and TLR7 signaling in the control of SARS-CoV-2." (PMID 37158982, 2023). "Compared to TLR7 and TLR9, a dramatically elevated level of TLR8 was shown in neutrophils after treatment with COVID-19 patient–derived EVs (MFI, 92.97 ± 25.07 versus 24.48 ± 5.03, P < 0.005), and this effect was suppressed in the presence of the TLR8 specific inhibitor Cu-CPT9a." (PMID 37904132, 2023). "A recent study of COVID-19 patients showed that while TLR7 is expressed similarly in non-ICU patients of both sexes, TLR7 expression in blood cells is significantly downregulated in male patients admitted to the ICU as compared to female patients." (PMID 37063266, 2023). "We previously reported that impaired type I IFN activity, due to inborn errors of TLR3- and TLR7-dependent type I interferon (IFN) immunity or to autoantibodies against type I IFN, account for 15–20% of cases of life-threatening COVID-19 in unvaccinated patients." (PMID 37020259, 2023). "By contrast, expression of TLR4, TLR5, TLR6, and TLR7 was not altered in COVID-19-derived monocytes." (PMID 37310504, 2023). "It was observed that oxygen saturation, WBC count, Neutrophil–lymphocyte ratio, LDH level, CRP level, and ESR level had a significant positive correlation with the transcript levels of TLR3, TLR7, TLR8, and TLR9 in the COVID-19 Group A as well as COVID-19 Group B patients." (PMID 35538443, 2022). "It was observed that mRNA expression of TLR3 (fold change = 2.3, P = 0.016), TLR7 (fold change = 2.1, P = 0.033), TLR8 (fold change = 2.3, P = 0.022), and TLR9 (fold change = 2.4, P = 0.019) was significantly upregulated in the COVID-19- Group B versus Control-Group II." (PMID 35538443, 2022). "Thus, TLR7/8 was discovered as a critical cellular sensor of SARS-CoV-2 ssRNAs that takes part in host resistance and in COVID-19 development." (PMID 35847031, 2022). "There was a significant positive correlation between percentage of oxygen saturation and transcript levels of TLR3 (rho = 0.37, P = 0.041), TLR7 (rho = 0.30, P = 0.026), TLR8 (rho = 0.35, P = 0.022), and TLR9 (rho = 0.39, P = 0.028) in the overall COVID-19 cases." (PMID 35538443, 2022). "It was seen that mRNA expression of TLR3 (fold change = 2.2, P = 0.004), TLR7 (fold change = 2.5, P = 0.038), TLR8 (fold change = 3.1, P = 0.018), and TLR9 (fold change = 3.0, P = 0.026) was significantly upregulated in the COVID-19- Group A in comparison to Control-Group III." (PMID 35538443, 2022). "Interestingly, toll-like receptor 7 (TLR7), essential to trigger an antiviral response through the secretion of type I IFN-α/β, increases in moderate COVID-19 patients." (PMID 36325317, 2022). "Here in the current investigation, we attempted to measure the mRNA expression levels of TLR3, TLR7, TLR8, and TLR9 in the nasopharyngeal epithelial cells from COVID-19 patients in order to determine the role of these innate immune system molecules in the inflammatory settings of COVID-19 patients." (PMID 35538443, 2022). "Therefore, the analysis of the genotypes of TLR2, TLR3, TLR4, TLR6, TLR7, TLR8, and TLR9 is important for the study of COVID-19." (PMID 35327350, 2022).
COVID-19 (continued). "Recently, two studies in young men with severe COVID-19 and no history of major chronic diseases identified rare loss-of-function (LOF) variants in X-chromosomal TLR7 that were associated with impaired TLR7 signaling as well as type I and II IFN responses." (PMID 34952932, 2022). "In contrast to STING and IRF3 expression, upregulation of TLR7 was seen in both STs, and CTs in COVID-19 exposed placentas (h and h1) compared to non-COVID controls (c and c1)." (PMID 36743911, 2022). "As TLR7 and type I IFN signaling are involved in COVID-19, we can hypothesize that aCL generated during the infection could signal through the recently described EPCR-LBPA pathway involved in inflammation and thrombosis." (PMID 35869087, 2022). "Modulation of TLR3, TLR7, TLR8, TLR9 in the epithelial cells of COVID-19 cases may estimate the disease severity and requirement for hospitalization." (PMID 35538443, 2022). "We found that COVID-19 plasma exosomes significantly induced the expression of TLR3 and TLR9 in all subsets of immune cells tested, while COVID-19 plasma exosomes were unable to induce TLR7 expression in CD8+ T cells." (PMID 36526691, 2022). "We know that the activation of TLR7/8 induces the production of type 1 and type 2 IFN as well as pro-inflammatory cytokines, where the production defect in hemizygous males leads to severe COVID-19." (PMID 34889978, 2022). "In this report, we demonstrate that COVID-19 plasma exosomes stimulate protein expression of TLR3 as well as TLR7 and TLR9 in CD4+ T cells, CD8+ T cells, and CD14+ monocytes compared with cells that remained untreated, treated with plasma exosomes from non-COVID-19 or healthy donors, or poly(I:C)." (PMID 36526691, 2022). "In a larger cohort of 1202 patients with life-threatening pneumonia aged below 60 years of age from the COVID-19 HGE, X-linked TLR7 deficiency was diagnosed in 17 (1.4%) patients but not in the 331 male controls." (PMID 35986347, 2022). "Factors that may exacerbate COVID-19 morbidity through hyperinflammatory states include increases in the complement system, increases in TLR-1 and TLR-7, and increased pro-inflammatory cytokines such as IL-6 and TNFα." (PMID 35955740, 2022). "In addition, a significant positive correlation was detected between WBC count and transcript levels of TLR3 (rho = 0.55, P = 0.020), TLR7 (rho = 0.59, P = 0.029), TLR8 (rho = 0.44, P = 0.012), and TLR9 (rho = 0.41, P = 0.034) in the whole COVID-19 cases." (PMID 35538443, 2022). "An experimental or clinical study that examines sex differences in the TLR7 and type 1 IFN response in COVID-19 is necessary to further explore this hypothesis." (PMID 34858409, 2021). "In conclusion, patients suffering from MAFLD could suffer a chronic stimulation of TLR7/8 and TLR4 in the alveolar macrophages, which make them more vulnerable to severe COVID-19." (PMID 33859644, 2021). "Low TLR7 and TLR8 levels in MetS and COVID-19 comorbidity may reduce myocardial capacity to generate an antiviral response and thus blunt the immune response." (PMID 34611227, 2021). "In particular, severe COVID-19 patients (as well as influenza-associated ALI/ARDS) are characterized by the activation and increased expression of TLR3 and TLR7—two virus-activated receptors—while NOD2 does not appear to play a major role." (PMID 33672738, 2021). "In various articles calling for investigation of TLR7 agonist or IFN administration early in COVID-19, sex is also not named as a factor to be taken into account." (PMID 34858409, 2021). "Applying these criteria resulted in two top predicted sex-biased genes, including TLR7 and Bruton tyrosine kinase (BTK), which may explain the sex-specific disease severity of COVID-19." (PMID 34330889, 2021). "TLR7 and BTK are male-biased genes in peripheral monocytes with severe COVID-19." (PMID 34330889, 2021).
COVID-19 (continued). "In sum, the activation of TLR2, TLR4, TLR7, TLR9 and NLRP3 are almost certainly maintained by DAMPs in severe COVID-19, ALI/ARDS and sepsis and may need to be therapeutically addressed." (PMID 33672738, 2021). "Furthermore, the downstream factors of TLR7 and BTK in TLR pathway, such as MYD88, IRF7, NFKB1, and JUN, and cytokines (TNF, IL1B, and IL18) were elevated in men with severe COVID-19." (PMID 34330889, 2021). "Innate immune receptor activation or inactivation has not been studied extensively for severe COVID-19-associated ARDS, but consistent evidence exists for the activation of TLR4, TLR7 and NLRP3." (PMID 33672738, 2021). "By contrast, the involvement of TLR7/8 in the immune response against SARS-CoV-2 and role in COVID-19 pathogenesis and therapeutic potential has only been hypothesized." (PMID 34375313, 2021). "Other possible DAMPs that may be playing roles in COVID-19 include extracellular RNAs that can activate TLR3 and TLR7, as well as extracellular hemoglobin, which activates NLRP3 and is associated with coagulation dysregulation and microclotting." (PMID 33672738, 2021). "Altogether, monocyte-specific expression of TLR7 and BTK may provide potential explanations for the male-biased disease severity in COVID-19." (PMID 34330889, 2021). "This may be due to TLR7/8 recognizing antiphospholipid antibodies (aPL) (a TLR7/8 activating DAMP), which have been shown to be upregulated in COVID-19 patients." (PMID 33498183, 2021). "To test this, we performed ex vivo stimulation of PBMCs from healthy or COVID-19–infected individuals, using a mixture of synthetic TLR7 and TLR 8 (TLR7/8) and TLR3 ligands, which are known to be expressed by viruses, and we performed an intracellular staining assay to detect cytokine responses." (PMID 32788292, 2020). "Treatment of these whole blood samples with the small molecule R848, a mimic of TLR7 and TLR8 activation by single strand RNA, increased the percentage of IL-6+ blood monocytes, with significantly higher levels in samples from COVID-19 patients compared to healthy controls." (PMID 32503877, 2020). "Although TLR7 can activate both NF-κB and IRFs, in turn inducing inflammatory and antiviral responses, during SARS-CoV-2 lung infection, TLR7 has been shown to mainly activate the NF-κB pathway contributing to the overt production of pro-inflammatory cytokines in patients with severe COVID-19." (PMID 38390874, 2024). "The COVID-19 patient–derived EVs-induced NETs formation was suppressed completely in the presence of the vacuolar type H+-ATPase inhibitor bafilomycin A1 (BafA1, 100 nM), suggesting that endolysosomal TLRs such as TLR3, TLR7, TLR8 and TLR9 mediate NETs formation." (PMID 37904132, 2023). "To dissect the regulatory mechanism of COVID-19 patient–derived EV-induced proinflammatory cytokines/chemokines upregulation, we used the HEK-hTLR7/8 cell model (Invivogen, USA) to examine COVID-19 patient–derived EVs and miR21/let-7b-loaded pEVs modulation on NF-κB activity upon TLR7/8 engagement." (PMID 37904132, 2023). "In conclusion, low secretion of IL-8 was observed upon stimulation with TLR2, TLR4, TLR7/8, TLR9, and NOD2 agonists by the blood cells of COVID-19 patients at hospital admission and was restored after two weeks of hospitalization, which may be a contributing factor to immunosuppression." (PMID 37189696, 2023). "However, to the best of our knowledge, it has not yet demonstrated the role of ACE2, TMPRSS2, and TLR7 in the different outcomes of COVID-19 between men and women." (PMID 36768959, 2023). "Notably, SARS-CoV-2 has been shown to activate both TLR7/855, and TLR456, therefore both the R848 and LPS stimulated responses may mimic the in vivo anti-COVID-19 responses." (PMID 36101705, 2022). "In addition, COVID-19 plasma exosomes stimulated expression of TLR3, TLR7, TLR8, and TLR9 by PBMC." (PMID 36526691, 2022).
COVID-19 (continued). "Therefore, TLR7 function, together with type I and II IFN response, is likely to be of paramount importance to avoid severe COVID-19, which is largely related to viral load and persistence, resulting in diffuse damage of lung cells and plasma protein leakage into alveolar spaces." (PMID 34718937, 2022). "Subsequently, supernatants were analyzed for IL-6 amounts, as this cytokine is primarily released from iMGL activated by RNA-based TLR7/8 agonists (data not shown) and its concentration in the cerebrospinal fluid (CSF) of a subset of COVID-19 patients is increased." (PMID 36713399, 2022). "TLR7 agonists with several modes of administration are already available for other inflammatory diseases with various degrees of efficacy and would need further examination for use in COVID-19, but, no clinical trial was started." (PMID 34858409, 2021). "Critical COVID-19 and seasonal influenza can be caused by inborn errors of TLR3-dependent type I IFN immunity, but susceptibility to these infections is not allelic at the TLR7 locus." (PMID 34413140, 2021). "Although TLR7 stimulation with SARS-CoV-2 was not directly examined, this study suggests that TLR7-mediated IFN responses might protect against COVID-19 progression." (PMID 33062077, 2020). "Additionally, analysis of DNA methylation patterns on the TLR7 gene revealed four differentially methylated positions that were significantly different between men with severe and mild COVID-19, whereas there were no significant TLR7 methylation differences between females." (PMID 37063266, 2023). "For instance, the expression of the toll-like receptor 7 (TLR7) gene located on the X chromosome and CD4+/CD8+ T-cell ratio are higher in women, indicating that differences in host immune response may explain a portion of the sex differences in disease severity in COVID-19." (PMID 34835015, 2021). "Furthermore, reduction of E2-2 expression upon TLR7 stimulation for pDC exhaustion in other viral infections, is a likely mechanism driving pDC hypo-functionality in COVID-19 patients, although E2-2 levels have not been studied in pDC from SARS-CoV-2 infected cohorts." (PMID 34578420, 2021). "Our results also demonstrate the effects of TLR7 deficiency and impaired IFN/ISG responses on lung virus titers, antiviral/inflammatory responses, and pulmonary damage, all of which could not be evaluated in COVID-19 patients because of the lack of human autopsy or lung biopsy samples." (PMID 40162785, 2025). "In the current investigation, we determined the expression levels of TLR3, TLR7, TLR8, and TLR9 in the epithelial cells obtained from confirmed COVID-19 cases with and without different clinical symptoms." (PMID 35538443, 2022). "There was no significant upregulation of TLR3, TLR7, TLR8, and TLR9 in the epithelial cells from COVID-19-Group C compared to Control-Group I, Control-Group II, and Control-Group III." (PMID 35538443, 2022). "Several studies have suggested the role of TLRs in enhancing humoral responses during COVID-19 infection, but so far, no study has examined the expression of TLR3, TLR7, TLR8 and TLR9 on respiratory epithelial cells from COVID-19 patients." (PMID 35538443, 2022). "However, in an in vitro study, it has been shown that SARS-CoV-2 induces a TLR7/8-dependent type I and III IFN response in peripheral blood mononuclear cells, which could be protective or may contribute to the cytokine storm observed in COVID-19 and requires future investigation." (PMID 34835108, 2021). "However, due to the simultaneous release of pro-inflammatory cytokines and chemokines, activation of TLR7/8 during SARS-CoV-2 may provoke an augmented inflammatory response, which could result in severe and potentially lethal immunopathological consequences experienced by COVID-19 patients." (PMID 33498183, 2021).